SLCO5A1 (solute carrier organic anion transporter family member 5A1)
Synonyms: OATP-RP4; OATPRP4; OATP5A1; SLC21A15; OATP-J; OATPJ
Tractability: Antibody: its Gene Ontology location is reachable by antibodies, with high confidence; UniProt places it where antibodies can reach, with medium confidence; UniProt predicts a signal peptide or a membrane-spanning region; the Human Protein Atlas places it where antibodies can reach.
Gene: Protein-coding gene on chromosome 8 (69,667,041 to 69,835,064, reverse strand). Ensembl gene ENSG00000137571.
Subcellular location: Cell membrane
Subcellular location (Human Protein Atlas): Plasma membrane; Vesicles
Gene Ontology:
Molecular function: secondary active transmembrane transporter activity; transmembrane transporter activity
Biological process: sodium-independent organic anion transport; transmembrane transport
Cellular component: plasma membrane; basolateral plasma membrane; membrane
Genetic constraint (gnomAD): Loss-of-function variants: 46 observed, 70.8 expected, observed/expected ratio (o/e) 0.65, 90% interval 0.51 to 0.83. The upper end of that interval is the gene's LOEUF score, 0.83, which puts it in group 3 of 6, group 1 being the genes least tolerant of losing a copy. Missense variants: 1,019 observed, 1,110.6 expected, observed/expected ratio (o/e) 0.92, 90% interval 0.87 to 0.97. Synonymous variants: 435 observed, 433.89 expected, observed/expected ratio (o/e) 1, 90% interval 0.93 to 1.09.
Homologues: Orthologues: chimpanzee SLCO5A1 (99% identical), macaque SLCO5A1 (98% identical), dog SLCO5A1 (92% identical), rabbit SLCO5A1 (91% identical), pig SLCO5A1 (91% identical), guinea pig SLCO5A1 (89% identical), mouse Slco5a1 (89% identical), rat Slco5a1 (88% identical), tropical clawed frog slco5a1 (75% identical), zebrafish slco5a1a (69% identical), Drosophila melanogaster Oatp74D (23% identical), Drosophila melanogaster Oatp33Ea (22% identical), and 8 more. Paralogues in human: SLCO4A1 (29% identical), SLCO3A1 (28% identical), SLCO4C1 (28% identical), SLCO2B1 (25% identical), SLCO1B3 (24% identical), SLCO2A1 (24% identical), SLCO1B1 (23% identical), SLCO1C1 (23% identical), SLCO1A2 (22% identical), SLCO6A1 (21% identical).
Diseases named in the same sentence as SLCO5A1 in open-access papers:
SLCO5A1 is named in the same sentence as 22 diseases in open-access papers, as found by Europe PMC text mining. Sharing a sentence is not in itself a finding about the gene and the disease. The quoted sentences say what the papers report.
breast carcinoma (3 papers, 2013 to 2025). "In the gene-level analysis, we found two significant genes (SLCO5A1 and SULF1, P < 0.05 after Bonferroni correction) associated with breast cancer survival." (PMID 31949161, 2020).
mesomelia-synostoses syndrome (2 papers, 2014 to 2024). "8q13 has also reportedly been associated with Mesomelia-Synostoses syndrome (MSS, OMIM 600383) due to the co-deletion of SULF1 and SLCO5A1." (PMID 25135225, 2014).
prostate carcinoma (2 papers, 2022 to 2023). A carcinoma that arises from epithelial cells of the prostate gland. "In some studies, the SNP(single nucleotide polymorphism) in SLCO5A1 was correlated with the clinical staging of prostate cancer." (PMID 36052234, 2022).
small cell lung carcinoma (2 papers, 2013 to 2020). Small cell lung cancer (SCLC) is a highly aggressive malignant neoplasm, accounting for 10-15% of lung cancer cases, characterized byrapid growth, and early metastasis. "Expression of both transporters has been detected in several cancers; for SLCO5A1, these include breast, bone, prostate, liver and small cell lung cancer." (PMID 32388639, 2020). "SLCO5A1 was also found in drug-resistant small cell lung cancer (SCLC) cells, primary liver cancer and liver metastases from colon tumors." (PMID 24376674, 2013).
breast tumors (1 paper, 2018). "Furthermore, there is a general lack of studies on a potential prognostic effect of OATP5A1 for cancer patients; however, SLCO5A1 expression has been reported in a number of tumors and the localization of the OATP5A1 protein has been shown in liver and breast tumors." (PMID 30131693, 2018).
neuroblastoma (1 paper, 2019). Neuroblastoma (NB) is the most common solid, extracranial childhood tumor. "The other RNAs considerably over-expressed in MYCN-amplified neuroblastoma cell lines were RP11-102F4.3, RNF217, GRIK3, and SLCO5A1." (PMID 31690716, 2019). "Here our RNA sequencing analysis identifies N-Myc, MYCNOS, IGF2BP1, lncNB1, RNF217, RP11-102F4.3, GRIK3, and SLCO5A1 as the RNAs most considerably over-expressed in MYCN-amplified, compared with MYCN-non-amplified, neuroblastoma cell lines." (PMID 31690716, 2019).
opioid use disorder (1 paper, 2024). A substance-related disorder that involves the recurring use of opioids despite negative consequences. "We identified three genes linked to impulsivity—SLCO5A1, PRKCA, and PRKCH—in infants born to mothers with opioid use disorders." (PMID 39238930, 2024).
cancer (5 papers, 2014 to 2024). A tumor composed of atypical neoplastic, often pleomorphic cells that invade other tissues. "Although other members of the OATP family are expressed in some types of tumors and can transport antitumor drugs, such as OATP1C1 (SLCO1C1), which transports docetaxel, OATP4C1 (SLCO4C1), methotrexate, and OATP5A1 (SLCO5A1), satraplatin, their role in cancer chemoresistance is poorly understood." (PMID 39143954, 2024).
tumor (4 papers, 2018 to 2025). "Given that the FGFR1::SLCO5A1 fusion was detected in the primary tumour but not in the metastatic focus, it is possible that this represents a random event rather than a pathogenic alteration." (PMID 40177273, 2025). "In addition, our data suggested that the expression levels of ATP11 C, CSE1L, SLC39A14, SLCO5A1, and GLS were higher in tumor tissues than in normal tissue by a factor of 3.4, 4.7, 2.8, 1.7 and 3.6, respectively." (PMID 34516344, 2021).
SLCO5A1 also shares sentences with these, for which no sentence is quoted: alcohol dependence (2 papers); Alzheimer disease (2); Anxiety (2); dementia (2); depression (2); encephalomyopathy (2); gastric cancer (1); juvenile myoclonic epilepsy (1); liver cancer (1); neurodevelopmental disorder (1); ovarian carcinoma (1); serous ovarian cancer (1); uveal melanoma (1).